PPARA (peroxisome proliferator activated receptor alpha)
Diseases named in the same sentence as PPARA in open-access papers (continued):
Sharing a sentence is not in itself a finding about the gene and the disease.
Sepsis (84 papers, 2010 to 2026). Sepsis is defined as life-threatening organ dysfunction caused by a dysregulated host response to infection. "In conclusion, these findings suggest that the loss of HNF4α and PPARα function during sepsis disrupts Nr1i3 transcription, thereby impairing CAR activity." (PMID 40904458, 2025). "In the current paper, we show that HNF4α loses its function in liver during sepsis, and that this loss-of-function is responsible for the PPARα-mediated problems we observed previously, as well as many others." (PMID 39261648, 2024). "Recently, it was demonstrated that PPARα mRNA and protein levels are downregulated upon sepsis due to HNF4α loss of function." (PMID 39456859, 2024). "In conclusion, hepatic HNF4α activity is decreased during sepsis, causing PPARα downregulation, metabolic problems, and a disturbed IL6-mediated acute phase response." (PMID 39261648, 2024). "This study shows that loss of hepatic HNF4α activity in sepsis disrupts PPARα-regulated lipid metabolism and the acute phase response, both of which can be restored by the agonist NCT." (PMID 39261648, 2024). "Fenofibrate, a PPARα agonist, also enhanced bacterial clearance in sepsis caused by Salmonella typhimurium." (PMID 36820088, 2023). "Sepsis is also associated with a rapid decline in hepatic PPARα mRNA and protein levels, and hence a reduced hepatic FFA β-oxidation catabolism." (PMID 37006237, 2023). "As a consequence of PPARα malfunctioning, ectopic deposition of lipids in the liver and kidney occur during sepsis and thereby cause lipotoxicity and tissue damage rather than production of energy." (PMID 37006237, 2023). "The two main transcription factors involved in the metabolic reprogramming during sepsis in the liver are the GR and PPARα, associated with hypoglycemia and hyperlactatemia, and increased levels of FFAs and glycerol in the blood." (PMID 37006237, 2023). "A significant association exists between CYP3A4 rs35599367 polymorphism with neurotoxicity and nephrotoxicity and between PPARA rs4253728 and rs4823613 polymorphism with sepsis in Pakistani liver transplant recipients taking tacrolimus." (PMID 36246675, 2022). "MG53 supplements can likewise protect the heart from myocardial dysfunction caused by sepsis by up-regulating PPARα expression." (PMID 36479346, 2022). "Mice deficient in PPARα have poorer kidney function with sepsis-induced AKI, which is also related to reduced FAO and increased inflammation." (PMID 35308207, 2022). "PPARα exhibits a protective role against sepsis-associated AKI by improving reduced FAO and increased inflammation." (PMID 35308207, 2022). "In a mouse model of sepsis, LPS administration rapidly caused downregulation of PPARα, PPARδ, as well as isoforms of thyroid hormone receptor (TR) and RXR (which are required for PPAR transcriptional activity) in the heart." (PMID 34575939, 2021). "We demonstrate that sepsis leads to a starvation response that is hindered by the rapid decline of hepatic PPARα levels, causing excess free fatty acids, leading to lipotoxicity, and glycerol." (PMID 31916705, 2020). "Previous research has demonstrated that peroxisome proliferator‐activated receptor α (PPARα) expression is associated with reduced organ system failure in sepsis." (PMID 31102342, 2019). "Using an experimental model of polymicrobial sepsis, we demonstrate that mice deficient in PPARα have worse kidney function, which is likely related to reduced fatty acid oxidation and increased inflammation." (PMID 31102342, 2019). "In conclusion, we have shown an association between PPARα expression and sepsis‐associated AKI in our experimental model." (PMID 31102342, 2019). "Although HNF4α loss-of-function in sepsis affects the chromatin state, PPARα activity, lipid metabolism, and the APR, its impact on the activity of other nuclear receptors remains unclear." (PMID 40904458, 2025).
Sepsis (continued). "We found that sepsis causes a progressive hepatic loss-of-function of HNF4α, which has a strong impact on the expression of several important nuclear receptors, including PPARα." (PMID 39261648, 2024). "Collectively, our results indicated that inflammation caused by infection leads to a disorder of liver lipid metabolism and that ANGPTL8 deficiency improves the survival rate of mice with sepsis by suppressing the inflammatory response and improving PGC1α/PPARα-mediated lipid metabolism." (PMID 39019343, 2024). "Since hepatic peroxisome proliferator-activated receptor alpha (PPARα) and glucocorticoid receptor (GR) quickly lose function in sepsis, these metabolites accumulate (causing toxicity) and fail to yield energy-rich molecules such as ketone bodies (KBs) and glucose." (PMID 37006237, 2023). "Elucidation of the upstream signal(s) causing PPARα dysfunction might uncover novel therapeutic opportunities in sepsis." (PMID 36552845, 2022). "In a murine model of sepsis, liver PPARα expression was significantly associated with survival." (PMID 33424957, 2020). "Moreover, we have clearly demonstrated that PPARα activity drops dramatically during sepsis, causing severe metabolic alterations." (PMID 31916705, 2020). "In the current work, we sought to further evaluate the role of PPARα in sepsis‐associated AKI." (PMID 31102342, 2019). "Furthermore, expression of the lipid-responsive transcription actor peroxisome proliferator–activated receptor α (PPARα) is decreased in patients with sepsis, and decreased PPARα is associated with increased bacterial burden and mortality in a rodent sepsis model." (PMID 36417534, 2022). "Switch in the expression of the PAR‐bZIP family members may relate to compromised xenobiotic metabolism associated with poor outcome in treated critically ill septic patients while loss of PPARA may impede liver's ability to adapt its metabolic activities during sepsis." (PMID 32407006, 2020). "We then observed that it was significantly downregulated in hepatic tissue of SLI mice and PPARα agonist WY-14643 effectively blocked sepsis-induced hepatic ferroptosis." (PMID 41712604, 2026). "Upon ischemia/reperfusion and sepsis, cardiac PPARα expression is typically downregulated, contributing to impaired fatty acid breakdown and reduced metabolic flexibility." (PMID 42193950, 2026). "This contrasts with previous studies of acute sepsis, where PPARα agonism was reported to reduce mortality and inflammation in rodent sepsis." (PMID 41365288, 2025). "Studies have confirmed that hydrogen, mediated by PPARα and its regulation of ABC efflux transporters, reduces the permeability of the blood–brain barrier and can prevent brain dysfunction caused by sepsis." (PMID 40362233, 2025). "Pharmacological activation of PPARα with PF appeared safe and well‐tolerated in our standardised murine model of prolonged sepsis, as mortality and illness severity were seemingly unaffected." (PMID 41365288, 2025). "In sepsis, failure of peroxisome proliferator-activated receptor α (PPARα) and glucocorticoid receptor (GR), which control these processes, causes accumulation of FFAs, glycerol, amino acids and lactate, as well as shortage in ketones and glucose." (PMID 39261648, 2024). "In these HNF4α knockout mice, PPARα expression and activity are low, and blood free fatty acid levels and hepatic lipid content are further increased in the context of sepsis." (PMID 39261648, 2024). "Altogether, HNF4α LOF in sepsis downregulates the expression of many nuclear receptors, including PPARα." (PMID 39261648, 2024). "Consistent with previous reports, we observed that sepsis inhibited PPARα expression, leading to impaired cardiac energy metabolism and impaired cardiac function." (PMID 38641695, 2024). "Specifically, hepatic HNF4α failure in sepsis mediates lipid dysfunction, downregulates several nuclear receptors, including PPARα, and diminishes IL6-mediated acute phase signaling." (PMID 39261648, 2024).
Sepsis (continued). "Many studies have shown abnormal expression of PPARα and PPARγ in the pathological state of sepsis, which is closely related to patient prognosis." (PMID 39019343, 2024). "During sepsis, however, the hepatic PPARα expression, which transcriptionally controls these processes, is reduced, leading to the accumulation of free fatty acids in the blood and liver, causing toxicity." (PMID 39261648, 2024). "Regarding sepsis, interestingly, the beneficial potential of fibrates has been far less examined than statins, although they act similarly to statins via PPARα activation." (PMID 38203431, 2023). "Gemfibrozil prevents sepsis-induced microcirculatory aberrances in the colon and liver PPARα-independently." (PMID 38203431, 2023). "Determination of hepatic PPARα levels and function in human sepsis patients is, however, challenging, primarily due to the coagulation problems in sepsis patients." (PMID 36552845, 2022). "Preventing PPARα dysfunction reduces sepsis mortality, making this pathway an interesting target to evaluate in clinical research." (PMID 36552845, 2022). "This correlation implies that pigs with lower PPARα levels have a higher need for NE infusion to maintain their blood pressure, which is indicative of a more severe sepsis." (PMID 36552845, 2022). "Our results strengthen the potential validity of poor PPARα signaling as a new therapeutic target for human sepsis patients." (PMID 36552845, 2022). "Clinical data indicated that genome-wide expression profiles are characterized by repression of the PPARα signaling pathway with increased incidence of severe sepsis in AKI." (PMID 35308207, 2022). "The data obtained in porcine septic subjects thus confirm the results obtained in murine sepsis and support the potential of targeting defective PPARα signaling in the clinic." (PMID 36552845, 2022). "Together, these data support the notion that PPARα signaling is dysfunctional in the liver of septic pigs and correlates with sepsis severity." (PMID 36552845, 2022). "PPARα expression and activation protects the body from sepsis by promoting an appropriate metabolic response." (PMID 36212144, 2022). "The median LFC of these genes was −0.27 and significantly differed from the baseline LFC 0, which confirms that PPARα appears significantly less active as a transcription factor in sepsis than sham pigs." (PMID 36552845, 2022). "Despite the essential role of PPARα to cope with starvation, recent studies in murine sepsis have found that PPARα expression dramatically declines and hence loses function in the liver." (PMID 36552845, 2022). "The role of peroxisome proliferator-activated receptor alpha (PPARα) in liver dysfunction during sepsis has recently been described, and restoring PPARα signaling has proven to be successful in mouse polymicrobial sepsis." (PMID 36552845, 2022). "Analysis of the downregulated genes with Wiki pathway analysis identified PPARα signaling as most affected pathway during sepsis." (PMID 36552845, 2022). "The study also found that although PPARα messenger ribonucleic acid (mRNA) expression and its transcriptional targets in sepsis decreased, there was a transient increase 24 h after CLP before the decline in these proteins." (PMID 34300048, 2021). "We have confirmed this finding and found that hepatic PPARα function and signaling are altered at a genome‐wide level during sepsis, with deleterious effects on liver metabolic functions and health as a consequence." (PMID 31916705, 2020). "We have shown that hepatic PPARα transcriptional function is severely dampened during sepsis, potentially due to a drastic decrease in hepatic PPARα mRNA and protein levels." (PMID 31916705, 2020). "In conclusion, our study illustrated that microRNA-21 exacerbate acute liver injury in sepsis mice by inhibiting PPARα expression." (PMID 33424957, 2020).
Sepsis (continued). "In conclusion, our results demonstrate that sepsis leads to an abnormal starvation response and major metabolic aberrations through acute activation of lipolysis in fat tissue and downregulation of PPARα in the liver." (PMID 31916705, 2020). "Together, these data suggest a fast and strong downregulation of PPARα mRNA and protein levels in liver during sepsis." (PMID 31916705, 2020). "Hepatic PPARα was recently shown to be crucial for survival during sepsis, induced by bacterial infection in mice, by controlling the metabolic response in hepatocytes." (PMID 31916705, 2020). "This study highlights the contribution of lipid metabolic dysfunction to the pathology of sepsis, and downregulation of hepatic PPARα as a key factor in the metabolic dysregulation during sepsis." (PMID 31916705, 2020). "To investigate the molecular mechanisms of miR-21 in sepsis, we used TargetScan to identify the potential genes, and PPARα was found to be one of the most relevant genes to sepsis." (PMID 33424957, 2020). "Recently, Paumelle and colleagues have demonstrated that appropriate function of hepatic PPARα is crucial for survival of sepsis, induced by a bacterial infection in mice." (PMID 31916705, 2020). "Subsequently, we found that in the liver of sepsis mice model, PPARα expression was decreased when miR-21 expression was increased." (PMID 33424957, 2020). "LncRNA colorectal neoplasia differentially expressed (CRNDE) protected against sepsis-induced kidney injury by inhibiting the proliferation and promoting the apoptosis of renal cells via the miR-181a-5p/PPARα pathway." (PMID 32972270, 2020). "Opposed to the strong and rapid decline of PPARα expression levels we observed during sepsis, this study reported an increase in PPARα levels in liver after E. coli infection." (PMID 31916705, 2020). "In conclusion, in LPS-induced sepsis mice model, we demonstrated that miR-21 contributed sepsis-induced liver injury and inflammation by inhibiting PPARα expression." (PMID 33424957, 2020). "This study illustrated that miR-21 suppression attenuated liver injury in LPS-induced sepsis mice, by potentiating PPARα expression, which suggested a contribution of miR-21 in the pathogenesis of sepsis-induced liver injury." (PMID 33424957, 2020). "Together, these data demonstrate a reprogramming of PPARα signaling during sepsis in which pro‐inflammatory signaling is favored to activation of metabolic pathways." (PMID 31916705, 2020). "In addition, many GW7647‐responsive genes, including PPARα itself, are being downregulated during sepsis, which may cause severe disturbances in fatty acid metabolic pathways such as breakdown of fatty acids via β‐oxidation, energy generation, and ketone body formation." (PMID 31916705, 2020). "As a consequence of the PPARα decline, some PPARα‐responsive genes such as Hmgcs2 follow the gradual decline in mRNA levels in liver after sepsis." (PMID 31916705, 2020). "In this study, we aim to explore the role of miR-21 and PPARα in the pathogenesis of sepsis-induced liver injury." (PMID 33424957, 2020). "A preliminary experiment suggests that the liver is crucial for the protective effect of pemafibrate in sepsis, since depletion of PPARα in the liver prevented pemafibrate‐mediated protection." (PMID 31916705, 2020). "In our sepsis model, we observed that PPARα loses its biological activity and that PPARα quickly declines in mRNA and protein concentration." (PMID 31916705, 2020). "We suggest the use of fibrates as adjunct therapy for the treatment of sepsis as they hold considerable therapeutic potential by improving hepatic PPARα function and metabolic function during sepsis." (PMID 31916705, 2020). "The decline in mRNA was reflected by significantly lower PPARA protein levels in liver 24 h after sepsis." (PMID 31916705, 2020). "In the mouse model, PPARα signaling was key to amelioration of inflammatory cytokine production during sepsis." (PMID 30897154, 2019).
Sepsis (continued). "We also show that a subgroup of children with sepsis whose genome‐wide expression profiles are characterized by repression of the PPARα signaling pathway has increased incidence of severe AKI." (PMID 31102342, 2019). "Poor outcomes in adult sepsis correlate with an inhibited ability to produce ketone bodies via PPARα." (PMID 30190719, 2018). "Currently, it remains uncertain whether pharmacological activation of PPARα may promote ketogenesis and affect muscle weakness during sepsis." (PMID 41365288, 2025). "Indeed, hepatic PPARα expression was found to be suppressed during sepsis, and, in critically ill children, suppression of whole blood PPARα was in proportion to the severity of illness." (PMID 41365288, 2025). "Suppression of the peroxisome proliferator‐activated receptor alpha (PPARα) has been related to poor outcomes in sepsis and may compromise ketogenesis during critical illness." (PMID 41365288, 2025). "Expression of the key nuclear transcription factor regulating lipid metabolism, PPARα (PPARa) and its co-activator PGC1α (Ppargc1a) were downregulated in acute sepsis, but increased above healthy levels in prolonged sepsis." (PMID 39821755, 2025). "Moreover, in animal models of sepsis, knockout of PPARα dysregulated the immune response and increased mortality, whereas PPARα agonists improved organ function and decreased mortality." (PMID 41365288, 2025). "In sepsis, limited food intake and increased energy expenditure induce a starvation response, which is compromised by a quick decline in the expression of hepatic PPARα, a transcription factor essential in intracellular catabolism of free fatty acids." (PMID 39261648, 2024). "Downregulation of hepatic PPARα in sepsis at the mRNA and protein levels hampers FFA β-oxidation." (PMID 39261648, 2024). "The downstream effects of HNF4α failure in sepsis has a strong effect on PPARα levels and consequent PPARα-mediated FFA consumption, as well as on the expression of several other nuclear receptor TFs in the liver, such as Liver X receptor-α (LXRα), RXRα and Farnesoid X receptor (FXR)." (PMID 39261648, 2024). "During sepsis, FFAs are released into the blood after lipolysis of triglycerides in white adipose tissue and are absorbed by the liver, leading to accumulation and subsequent lipotoxicity, likely due to PPARα LOF." (PMID 39261648, 2024). "In cecal ligation and puncture-induced sepsis, PPARα dysfunction is evident." (PMID 39071067, 2024). "During sepsis, there is a starvation response which is worsened by the rapid decline of hepatic peroxisome proliferator activated receptor alpha(PPARa) and PGC-1a levels, leading to poor mitochondria function, excess free fatty acids, lipotoxicity, and glycerol." (PMID 38727856, 2024). "Upon sepsis in wild-type mice, HNF4α is shown to lose its function, leading to PPARα reduction." (PMID 39456859, 2024). "Furthermore, inhibition of the master lipid sensor peroxisome proliferator-activated receptor alpha (PPARα) within hepatocytes exacerbates sepsis-induced pathology." (PMID 38305778, 2024). "It has been shown that PPARα is essential for sepsis survival." (PMID 37006237, 2023). "Next to GCR, sepsis is also characterized by a PPARα dysfunction in the liver." (PMID 37006237, 2023). "Since hypoxia is associated with increased lipolysis, increased FFA levels in the blood, and impaired FFA β-oxidation, and p300 functions as a co-activator for PPARα, hepatic HIF1α and/or HIF2α might be involved in the declined PPARα signaling during sepsis." (PMID 37006237, 2023). "Thus, PPARα exerts necessary effects on the inhibition of neuroinflammation during sepsis induced by H2." (PMID 37474902, 2023). "Also, mice treated with the PPARα antagonist GW6471 are more prone to CLP-induced polymicrobial sepsis." (PMID 37006237, 2023).